GLP1R (glucagon like peptide 1 receptor)
Diseases named in the same sentence as GLP1R in open-access papers (continued):
Sharing a sentence is not in itself a finding about the gene and the disease.
type 2 diabetes (continued). "Glucagon-like peptide-1 receptor agonists (GLP-1 RAs) are extensively used in the management of patients with type 2 diabetes mellitus (T2DM) and obesity." (PMID 40847331, 2025). "The management of type 2 diabetes has evolved significantly with the advent of incretin-based therapies, particularly dipeptidyl peptidase-4 inhibitors and glucagon-like peptide-1 receptor agonists." (PMID 40607140, 2025). "Glucagon-like peptide-1 receptor agonists (GLP-1RAs) are widely used in the management of type 2 diabetes and obesity due to their metabolic benefits." (PMID 41008649, 2025). "Initially developed for type 2 diabetes and obesity, glucagon-like peptide-1 receptor agonists (GLP-1RAs) are now emerging as promising candidates for modifying the course of neurodegenerative diseases." (PMID 41356006, 2025). "Glucagon-like peptide-1 receptor agonists, used for the treatment of type 2 diabetes, have been reported to exert two beneficial effects on pancreatic islet hormone secretion: the promotion of insulin secretion and the suppression of glucagon secretion." (PMID 40429740, 2025). "Glucagon-like peptide-1 receptor agonists (GLP-1RAs) are long-acting drugs that have gathered a lot of attention worldwide for their utility in the treatment landscape of type 2 diabetes mellitus and obesity." (PMID 40722592, 2025). "Background/Objectives: Sodium–glucose cotransporter-2 inhibitors (SGLT2i) and glucagon-like peptide-1 receptor agonists (GLP-1RA) have shown blood pressure (BP) reduction in type 2 diabetes (T2D)." (PMID 41156303, 2025). "Glucagon‐like peptide‐1 receptor (GLP‐1R) agonists are well‐established therapies for obesity and type 2 diabetes mellitus (T2DM)." (PMID 40860896, 2025). "This cohort study investigates the comparative risks of male external genital infections in adult male patients with type 2 diabetes treated with sodium-glucose cotransporter 2 (SGLT2) inhibitors vs glucagon-like peptide-1 receptor agonists (GLP-1RAs)." (PMID 41021225, 2025). "In 2005, glucagon-like peptide-1 receptor agonists (GLP-1 RAs) were approved to treat type 2 diabetes." (PMID 40172891, 2025). "Glucagon-like peptide-1 receptor agonists (GLP-1 RAs) have emerged as powerful agents in the management of type 2 diabetes mellitus (T2DM), offering glycemic control with added cardiovascular and renal benefits." (PMID 40777719, 2025). "Glucagon-like peptide-1 receptor agonists (GLP-1 RAs) are a popular first-line treatment option in managing Type 2 Diabetes Mellitus (T2DM) with cardiovascular co morbidities." (PMID 41323510, 2025). "Nevertheless, long-term GLP-1RA treatment has only slightly increased sodium excretion in people with type 2 diabetes, raising questions about the long-term impact of GLP-1R activation on the kidneys’ sodium handling and blood pressure control." (PMID 38540270, 2024). "The study further demonstrated that daphnetin has great value in preventing cognitive dysfunction in type 2 diabetes, and GLP-1R is a key potential target for the treatment of related diseases." (PMID 39257395, 2024). "GLP-1 RAs, or glucagon-like peptide-1 receptor agonists, are a class of injectable antihyperglycaemic medications used in the management of type 2 diabetes and obesity." (PMID 38791060, 2024). "Glucagon-like peptide-1 receptor agonists (GLP1-RAs) are an effective class of drugs for the treatment of type 2 diabetes mellitus (T2D), with well-defined safety and tolerability profiles." (PMID 38683498, 2024). "For patient_b with type 2 diabetes and a body mass index (BMI) of 28, it is recommended to consider the use of a glucagon-like peptide-1 receptor agonist (胰高糖素样肽-1受体激动剂) in addition to lifestyle interventions (生活方式干预) based on the SWRL rule." (PMID 38243204, 2024). "Glucagon-like peptide-1 receptor agonists (GLP-1 RAs) have been studied for their cardiovascular benefits in type 2 diabetes." (PMID 39003287, 2024).
type 2 diabetes (continued). "Glucagon-like peptide 1 receptor agonists (GLP-1 RAs), increasingly used for type 2 diabetes, show promise in reducing the cardiovascular risk, sparking interest in their effects on atherogenesis." (PMID 38929525, 2024). "Glucagon-like peptide-1 receptor agonists (GLP-1 RAs) have been used to reduce glucose levels in patients with type 2 diabetes mellitus since 2005." (PMID 38541083, 2024). "Second, patients with both asthma and type 2 diabetes and with a mean BMI of 39.5 ± 8.6 kg/m2 that were prescribed GLP-1R agonists exhibited fewer asthma exacerbations as compared to patients prescribed other classes of diabetic medications." (PMID 38878250, 2024). "Among glucose-lowering medications, glucagon-like peptide 1 receptor agonists (GLP-1RAs) are considered the first-line therapy in people with type 2 diabetes based on their metabolic and cardiovascular efficacy." (PMID 38470420, 2024). "Treatment with glucagon-like peptide-1 receptor agonists (GLP-1RAs) enables people with type 2 diabetes to achieve reductions in HbA1c and body weight." (PMID 38985162, 2024). "GLP1R analogs approved by the FDA are reliably used to treat type 2 diabetes and regulate glucose homeostasis." (PMID 39007271, 2024). "One class of drugs that have shown promise in clinical trials against type 2 diabetes are the so-called glucagon-like peptide 1 receptor (GLP-1R) agonists." (PMID 39339176, 2024). "Glucagon-like peptide-1 receptor (GLP-1R) agonists are now commonly used to treat type 2 diabetes and obesity." (PMID 38909126, 2024). "Semaglutide (Novo Nordisk, Denmark) is a glucagon-like peptide 1 receptor (GLP-1R) agonist initially designed to treat type 2 diabetes." (PMID 39462311, 2024). "Glucagon-like peptide-1 receptor agonists (GLP-1 RAs) are injectable antihyperglycemic medications known for effective glycemic control in type 2 diabetes mellitus, reducing glucose levels via insulin secretion and glucagon suppression." (PMID 39767190, 2024). "Survodutide (BI 456906) is a novel subcutaneous GCGR/GLP-1R dual agonist in development for the treatment of people with type 2 diabetes, obesity and non-alcoholic steatohepatitis (NASH)." (PMID 38095657, 2024). "Another GCGR/GLP-1R dual agonist, cotadutide, has been developed for the treatment of type 2 diabetes and obesity." (PMID 38095657, 2024). "Dulaglutide is a long-acting glucagon-like peptide-1 receptor agonist that is administered once weekly and approved for treating adults with type 2 diabetes mellitus." (PMID 38753098, 2024). "Recent studies reveal that glucagon-like peptide-1 receptor (GLP1R) agonists can improve mortality and left ventricular ejection fraction in the patients with type 2 diabetes and HF." (PMID 38782946, 2024). "Semaglutide is a glucagon-like peptide-1 receptor agonist (GLP-1RA) that has gained recent popularity in its effective management of type 2 diabetes mellitus (T2DM) and obesity." (PMID 39308839, 2024). "Semaglutide is a glucagon-like peptide-1 receptor agonists (GLP-1-RAs) approved for the treatment of type 2 diabetes mellitus (T2DM) at doses up to 1 mg." (PMID 39205685, 2024). "As such, agonists of the GLP-1 receptor (GLP-1R), exemplified by semaglutide and lixisenatide, are being developed for the treatment of type 2 diabetes and obesity." (PMID 38150382, 2024). "We compared the effects of sodium–glucose cotransporter 2 (SGLT2) inhibitors (SGLT2i) and glucagon-like peptide-1 receptor agonists (GLP-1RA) on renal outcomes in individuals with type 2 diabetes, focusing on the changes in eGFR and albuminuria." (PMID 39177691, 2024). "Glucagon-like peptide-1 receptor agonists (GLP-1RAs) are widely used clinically as blood glucose-lowering agents in the treatment of type 2 diabetes mellitus (T2DM), and these drugs also have a weight-lowering effect." (PMID 38834564, 2024).
type 2 diabetes (continued). "This cohort study investigates the risks of mortality and adverse cardiovascular and kidney outcomes among individuals with type 2 diabetes taking tirzepatide vs glucagon-like peptide 1 receptor agonists." (PMID 39133485, 2024). "Glucagon-like peptide-1 receptor agonists (GLP-1RAs) are essential in managing type 2 diabetes mellitus, promoting glucose regulation, weight reduction, and cardiovascular protection." (PMID 39429379, 2024). "The physiological effects of GLP-1, which include decreasing blood glucose levels and promoting satiety [for review], have led to the development of GLP-1 receptor (GLP-1R) agonists for managing type 2 diabetes and obesity [for review see]." (PMID 39221138, 2024). "Glucagon-like peptide-1 receptor (GLP-1R) agonists, such as liraglutide and semaglutide, have been developed for the treatment of both type 2 diabetes and obesity." (PMID 38095657, 2024). "Glucagon-like peptide-1 receptor agonists, specifically semaglutide and liraglutide, designed for type 2 diabetes mellitus treatment, have been explored as drugs for the treatment of obesity." (PMID 38742021, 2024). "GLP-1R agonists such as semaglutide have been approved for the treatment of type 2 diabetes and obesity." (PMID 38095657, 2024). "Glucagon-like peptide-1 receptor agonists (GLP-1RAs) have a reliable hypoglycaemic and weight-loss effect that can intervene in obesity, which is the basis of type 2 diabetes pathology." (PMID 39548500, 2024). "These include statins, PCSK9 inhibitors, antihypertensive medications, and novel glucagon-like peptide-1 receptor agonists (GLP-1 RAs) for type 2 diabetes and obesity treatment." (PMID 39731011, 2024). "As a GLP‐1 analog/GLP‐1R agonist, liraglutide is primarily used to treat type 2 diabetes mellitus because of its ability to lower blood glucose and body weight." (PMID 39159301, 2024). "The glucagon-like peptide-1 receptor (GLP-1R) agonists reduce glycated hemoglobin in patients with type 2 diabetes." (PMID 38915346, 2024). "Although less prominently, glucagon-like peptide-1 receptor agonists (GLP-1RA) can also attenuate renal dysfunction in type 2 diabetes." (PMID 39177691, 2024). "Although licensed as therapies for type 2 diabetes and obesity, interest has been gathered concerning the potential of glucagon-like peptide-1 receptor agonists (GLP-1 RAs) for AUD." (PMID 39764544, 2024). "Glucagon-like peptide 1 receptor agonists, such as Exendin-4, are one of the leading classes of Type 2 diabetes treatments but are prohibitively expensive." (PMID 40809148, 2024). "Glucagon-like peptide-1(GLP-1), a peptide hormone secreted by intestinal L-cells, has broad pharmacological potential for managing type 2 diabetes mellitus and metabolic syndrome-related disorders by binding to its receptor -GLP-1R." (PMID 38532900, 2024). "Randomised, placebo-controlled, cardiovascular outcomes trials of sodium–glucose co-transporter 2 inhibitors and glucagon-like peptide 1 receptor agonists in type 2 diabetes." (PMID 37734450, 2024). "Glucagon-like peptide-1 receptor agonists (GLP-1 RAs) have gained popularity in treating both type 2 diabetes and obesity." (PMID 39318780, 2024). "This cohort study compares anemia incidence between sodium-glucose cotransporter 2 (SGLT2) inhibitors and glucagon-like peptide-1 receptor agonists (GLP-1 RAs) among patients with type 2 diabetes and chronic kidney disease (CKD) stages 1 to 3 in Taiwan." (PMID 38436955, 2024). "Glucagon-like peptide-1 receptor (GLP-1R) agonists have effectively treated type 2 diabetes mellitus (T2DM) for many years." (PMID 38627765, 2024). "Glucagon-like peptide-1 receptor agonists (GLP-1 RAs) have emerged as a promising class of medications for type 2 diabetes (T2D) management." (PMID 39568487, 2024). "What is the association of tirzepatide vs glucagon-like peptide 1 receptor agonist (GLP-1 RA) treatment with all-cause mortality and adverse cardiovascular or kidney events in US patients with type 2 diabetes?" (PMID 39133485, 2024).
type 2 diabetes (continued). "Glucagon-like peptide-1 receptor agonists (GLP1-RAs) are a promising class of drugs for type 2 diabetes mellitus (T2DM)." (PMID 39458219, 2024). "In recent years, GLP-1 receptor (GLP-1R) agonists have proven highly effective in the treatment of obesity and type 2 diabetes." (PMID 39560873, 2024). "Glucagon-like peptide-1 receptor agonists (GLP-1 RAs) represent a major advancement in the pharmacological treatment of type 2 diabetes and obesity." (PMID 39498283, 2024). "A number of studies have shown that peptide agonists of the glucagon-like peptide 1 receptor (GLP1-R), which are licensed for the treatment of type 2 diabetes mellitus (T2DM), also have potent neuroprotective and anti-inflammatory properties." (PMID 38783166, 2024). "Glucagon-like peptide 1 receptor agonists (GLP1-ra) have been used for over a decade in the management of type 2 diabetes." (PMID 38584180, 2024). "In patients with type 2 diabetes, pioglitazone, glucagon-like peptide-1 receptor agonists, and sodium glucose cotransporter 2 inhibitors are recommended to improve liver fibrosis." (PMID 38730426, 2024). "This cohort study compares glucagon-like peptide 1 receptor agonists (GLP-1RAs) with 7 non–GLP-1RA antidiabetics among drug-naive patients with type 2 diabetes." (PMID 38060218, 2024). "Although GLP-1R agonists are widely used for common forms of type 2 diabetes, there are only three case study reports of their use in patients with lipodystrophy and few insights regarding their effects." (PMID 38745956, 2024). "The efficacy of glucagon-like peptide-1 receptor agonists (GLP1-RA) in type 2 diabetes mellitus is well-established." (PMID 38962634, 2024). "The development of glucagon-like peptide-1 receptor (GLP-1R) agonists for the treatment of type 2 diabetes and obesity has been accompanied by evidence for anti-inflammatory and cytoprotective actions in the heart, blood vessels, kidney, and brain." (PMID 39216535, 2024). "Patients treated with semaglutide, a glucagon-like peptide-1 receptor agonist (GLP-1RA) approved for treating type 2 diabetes (T2D) and for weight management have reported reduced desire to drink and smoke." (PMID 38486046, 2024). "Agonists of the glucagon-like peptide-1 receptor (GLP-1R) deliver significant beneficial effects both in treating type 2 diabetes and obesity." (PMID 38745956, 2024). "Glucagon-like peptide-1 receptor agonists (GLP-1 RAs) have been developed to manage type 2 diabetes mellitus." (PMID 39872560, 2024). "Previous studies have explored the effects of glucagon-like peptide-1 receptor agonists (GLP-1 RAs) in reducing cardiovascular events in type 2 diabetes." (PMID 39003287, 2024). "The effects of an extended GLP-1R activation on renal autoregulation in type 2 diabetes remain to be determined." (PMID 38540270, 2024). "Among the most widely used therapies targeting class B1 receptors are agonists of the glucagon-like peptide-1 receptor (GLP-1R) for the treatment of type 2 diabetes (T2D) and obesity." (PMID 38984948, 2024). "GLP-1R agonists continue to be used as glucose-lowering agents for type 2 diabetes based on their insulinotropic effect via pancreatic β-cells." (PMID 37930356, 2023). "This cohort study compares rates of 1-year adherence to glucagon-like peptide-1 receptor agonist or sodium-glucose cotransporter 2 inhibitor therapies by co-payment level among US adults with type 2 diabetes and/or heart failure." (PMID 37261826, 2023). "Therapies based on GLP‐1 receptor (GLP1R) agonism are now major players in the treatment of type 2 diabetes and obesity." (PMID 37638546, 2023). "Glucagon-like peptide-1 receptor agonists (GLP-1 RAs) have shown cardiovascular benefits in cardiovascular outcome trials in type 2 diabetes mellitus." (PMID 36966321, 2023). "The highest mean baseline EQ-5D index value was found in participants from trials in type 2 diabetes mellitus of glucagon-like peptide-1 receptor agonists and sodium glucose co-transporter 2 inhibitors 0.92 (0.09)." (PMID 36649256, 2023).
type 2 diabetes (continued). "In recent years, drugs targeting GPCRs have been the focus of efforts to improve treatments for type-2 diabetes and obesity, with GLP-1R agonists a particular success." (PMID 36943057, 2023). "Many glucagon-like peptide-1 receptor agonists (GLP-1 RAs) improve cardiovascular outcomes and albuminuria-based kidney endpoints in patients with type 2 diabetes at high cardiovascular risk." (PMID 37244998, 2023). "The GLP-1R is a highly effective target for managing type 2 diabetes by increasing insulin secretion, which lowers blood glucose levels." (PMID 37085847, 2023). "Tirzepatide is an agonist at both the GIPR and GLP-1R and is a highly effective treatment for type 2 diabetes and obesity." (PMID 37277609, 2023). "Recently, the first oral form of glucagon-like peptide-1 receptor agonist (GLP-1RA) semaglutide (Rybelsus®) has been launched as a treatment for type 2 diabetes and shown to potently ameliorate obesity as well as diabetes." (PMID 37686797, 2023). "For this reason, several existing medications to treat type 2 diabetes, such as dipeptidyl peptidase-4 inhibitors, glucagon-like peptide-1 receptor agonists, and sodium-glucose cotransporter-2 inhibitors, are being tested in subjects with T1D." (PMID 37296593, 2023). "Glucagon-like peptide-1 receptor agonists (GLP-1RAs) have gained traction for the management of type 2 diabetes and obesity." (PMID 37313232, 2023). "Six genes (CNR2, DPP4, GLP1R, SLC5A1, HTR2C, MCHR1) that encode therapeutic targets in development of type 2 diabetes or obesity." (PMID 36902588, 2023). "Effectiveness of glucagon-like peptide-1 receptor agonists (GLP-1RAs) versus long-acting insulins (LAIs) on preventing progressive chronic kidney outcomes is uncertain for type 2 diabetes (T2D) patients requiring intensive glycemic control." (PMID 37794465, 2023). "Glucagon-like peptide-1 receptor agonists (GLP-1RAs) were approved for the treatment of type 2 diabetes mellitus (T2DM) in 2005." (PMID 37431351, 2023). "Synthetic GLP-1R agonists are widely used to treat type 2 diabetes, in which the drugs demonstrate both peripheral and central effects (Hunter and Hölscher, 2012)." (PMID 37362000, 2023). "Asthmatics prescribed GLP-1R agonists for type 2 diabetes have been shown to have lower frequencies of asthma exacerbation." (PMID 37371472, 2023). "Until now, there are six synthetic GLP-1R agonists approved as pharmaceuticals to treat diabetes mellitus type 2, which have been derived from either GLP-1 itself or its paralogue exendin-4." (PMID 36769142, 2023). "GLP1R agonists, which are used to treat type 2 diabetes and obesity, have been shown to lower the incidence of cardiovascular death, myocardial infarction, and stroke." (PMID 37304960, 2023). "The current study found that glucagon-like peptide 1 receptor agonists can improve the islet secretion index of newly diagnosed type 2 diabetes patients." (PMID 37255814, 2023). "GLP-1R agonists are used to treat obesity and type 2 diabetes mellitus and have additional cardiovascular advantages beyond glycemic benefits." (PMID 37900360, 2023). "GLP-1R agonists like as liraglutide are currently widely used in the clinic as second-line therapy for type II diabetes, and GLP-1R agonists have been used in the clinical treatment of obesity in countries such as Korea and the United States." (PMID 37681442, 2023). "A series of GLP-1R agonists with resistance to dipeptidyl dipeptidase-IV breakdown are used routinely to treat type-2 diabetes and can be administered daily to weekly." (PMID 36943057, 2023). "In clinical trials, treatment with tirzepatide produced superior weight loss and glycemic control compared to GLP-1RAs3,17, suggesting that agonism at both the GIPR and GLP-1R is beneficial in humans with type 2 diabetes." (PMID 37277609, 2023). "Glucagon-like peptide 1 receptor agonists (GLP-1RAs) have changed considerably the management of type 2 diabetes (T2D)." (PMID 37656509, 2023).